CACNA1C (calcium voltage-gated channel subunit alpha1 C)
Diseases named in the same sentence as CACNA1C in open-access papers (continued):
Sharing a sentence is not in itself a finding about the gene and the disease.
Timothy syndrome (continued). "The first de novo variants in L-type Cavs were found in CACNA1C leading to Timothy syndrome, a multisystem disorder." (PMID 32583268, 2020). "LQTS-8 is a gain-of-function mutation of the CACNA1C-encoded α1C subunit of L-type Ca2+ channel (Cav1.2) and is generally associated with Timothy syndrome." (PMID 32161540, 2020). "In 2011, Yazawa and co-workers generated iPSC-CMs carrying a mutation causing a single amino acid substitution in exon 8a of CACNA1C (the gene encoding CaV1.2 in humans), causing Timothy syndrome." (PMID 33023024, 2020). "The final gene studied, CACNA1C, was found to have a definitive association with Timothy syndrome but only moderate evidence supporting a cardiac-only phenotype concordant with LQTS." (PMID 31983240, 2020). "The Timothy syndrome mutations, G402R, G402S and G406R in human CACNA1C, are of particular interest because each causes autism with high penetrance." (PMID 31805042, 2019). "We propose that the effect of CACNA1C variation in altering axon development is not limited to the Timothy syndrome mutation, but rather extends to the other autism-associated CACNA1C variants." (PMID 31805042, 2019). "For example, Timothy syndrome is caused by the G406R mutation in the CACNA1C gene, resulting in a gain of channel function by causing sustained Ca2+ influx, promoting APD prolongation and triggering early after-depolarization." (PMID 30929547, 2019). "The Timothy syndrome mutation in CACNA1C has the unusual property of being causative for autism with high penetrance, providing an opportunity to discover the downstream cellular processes that are perturbed to cause autism." (PMID 31805042, 2019). "The Timothy syndrome mutation is a rare de novo gain-of-function variant in CACNA1C that causes autism with high penetrance, providing a powerful avenue into investigating the role of CACNA1C variants in neurodevelopmental disorders." (PMID 31805042, 2019). "Although the Timothy syndrome mutation is rare with large effect, common variants with small effect in CACNA1C are also associated with autism." (PMID 31805042, 2019). "The Timothy syndrome mutation is actually a class of three rare de novo mutations in CACNA1C that encode either a G402R, G402S or G406R mutation in the CACNA1C protein." (PMID 31805042, 2019). "Some mutations in the CACNA1C gene were first identified in Timothy syndrome, causing extreme QT prolongation and SD18." (PMID 30279520, 2018). "A single amino acid substitution (G406R) in CACNA1C, the gene encoding for the L-type Ca2+ channel, is the cause of Timothy syndrome (long QT syndrome type 8 (LQT8), the most severe variant of LQTS because of its high mortality rate." (PMID 28721524, 2017). "Several point mutations have been described in CACNA1C as being associated with a rare multi-systemic syndrome called Timothy syndrome." (PMID 28146053, 2017). "Ever since mutation of the CACNA1C gene was found to be associated with Timothy syndrome (a syndromic autism) in 2004, neurogenic calcium dysregulation has been studied in ASD research." (PMID 27055244, 2016). "CACNA2D1 regulates influx of calcium ions into the cell upon membrane polarization and Mutations in a related gene (CACNA1C) are known to cause Timothy syndrome which includes neurological and developmental deficits and often autism symptoms." (PMID 26185613, 2015).
Timothy syndrome (continued). "Rare mutation in CACNA1C is suggested to cause Timothy syndrome, a disorder whose features include ASD-related phenotypes and intellectual disability." (PMID 26204268, 2015). "A particularly salient example of a perturbation in Cav1.2 function is Timothy syndrome (TS), a rare genetic disorder caused by dominant mutations in the gene CACNA1C, which encodes the α subunit of the voltage-gated calcium channel Cav1.2." (PMID 25360157, 2014). "Using whole-exome sequencing we identified a p.402G > S mutation in exon 8 of the gene CACNA1C in a family with two affected children, both presenting atypical form of Timothy syndrome (TS2)." (PMID 24773605, 2014). "By altering the kinetic parameters, the mutations are reminiscent of the CACNA1C mutation causing Timothy Syndrome, a Mendelian disease presenting with ASD." (PMID 24752249, 2014). "The p.G402S variant in exon 8 of the gene CACNA1C has been previously associated with Timothy Syndrome TS2 (MIM: 601005)." (PMID 24773605, 2014). "Mutations in CACNA1C have been found to lead to Timothy syndrome, a lethal disorder consisting of somatic symptoms like cardiac arrhythmia, and psychiatric symptoms like autism and cognitive disability." (PMID 23437284, 2013). "LQT8 and Timothy syndrome are caused by mutation in the CACNA1C gene encoding the L-type Ca2+ channel." (PMID 23015789, 2012). "One, rs10848653, is located in CACNA1C, a gene in which rare de novo mutations are responsible for Timothy syndrome, a Mendelian disorder that features ASD." (PMID 23241247, 2012). "The most salient prior genetic evidence implicating CCG in ASD comes from a CACNA1C gene mutation that results in Timothy syndrome (TS), a Mendelian disorder with delayed repolarization of the heart following a heartbeat." (PMID 23241247, 2012). "In LQT8, which is also known as the Timothy syndrome, mutations in the CACNA1C gene result in disturbed Cav1.2 channels." (PMID 23304551, 2012). "The mutations in the CACNA1C gene, which encodes the depolarizing long-lasting calcium current channel, are associated with Timothy syndrome, characterized by severe prolongation of the QT interval." (PMID 22496632, 2012). "Conversely, CACNA1C mutations associated with Timothy syndrome and LQTS8 typically produce a gain-of-function or altered channel gating, leading to prolonged action potentials and QT interval prolongation, which increase arrhythmia risk through different electrophysiological mechanisms." (PMID 40722809, 2025). "What is more, mutations in the CACNA1C gene, a voltage-gated calcium channel gene, are integral to the complex syndrome known as Timothy syndrome (LQT8), which is characterized by a highly malignant form of LQTS frequently presenting with a 2:1 functional AVB and multi-systemic disorders." (PMID 38339103, 2024). "Heterozygous mutations of CACNA1C, which is expressed in the Cav1.2 (α1C-containing) Ca2+ channels can cause a variety of disorders with cardiac arrhythmias as the leading symptom (Timothy syndrome, Brugada syndrome, Long-QT syndrome) with distinct genotype-phenotype correlations." (PMID 37065762, 2023). "Similarly, one can also envisage screening GOF CACNA1C variants in Timothy syndrome patients to identify the optimal drug for suppressing the late ICa,L without reducing peak ICa,L." (PMID 38089476, 2023). "In our systemic review we examined CACNA1C gene mutation associated Timothy syndrome, “cardiac only” Timothy syndrome, isolated long QT syndrome 8 and provided data that these disease forms exhibit major differences regarding clinical manifestations and outcome." (PMID 36523353, 2022). "We discuss different biochemical characteristics and clinical impacts of hypoglycemia in the context of CACNA1C variants and show that these may be associated with significant morbidity for Timothy Syndrome patients." (PMID 35897673, 2022).
Timothy syndrome (continued). "• Timothy syndrome is caused by heterozygous, gain of function variants in the CACNA1C gene. • Features include long QT interval, other ECG abnormalities, congenital heart defects, frequent infections because of altered immune response, and intermittent hypoglycemia." (PMID 33681094, 2021). "In humans, Timothy syndrome is also caused by a G406R mutation in CACNA1C." (PMID 31805042, 2019). "As the mechanisms by which CACNA1C affects axon development are unknown, studies of the Timothy Syndrome variant may uncover genetic mechanisms that also apply to the more common CACNA1C risk variants." (PMID 31805042, 2019). "Timothy syndrome is a very rare autosomal dominant disorder which results from mutations in the CACNA1C gene coding for the alpha-1 subunit of the L-type voltage-gated calcium channel Cav1.2." (PMID 30139379, 2018). "Finally, Timothy syndrome (TS) is a multi-system disorder which affects both the nervous and cardiac systems and is caused by a missense point mutation in the CACNA1C gene." (PMID 29875678, 2018). "Rare mutations of CACNA1C gene could cause Timothy Syndrome, a syndrome that leads to long QT intervals resulting in early death due to cardiac arrhythmias." (PMID 28765577, 2017). "If we had known that the patient had a genetic background of CACNA1C mutations, some of which were reported as cardiac-only Timothy syndrome, we could have avoided potential factors that triggered malignant TdP and VFs." (PMID 29258620, 2017). "Furthermore, rare mutation in CACNA1C is suggested to cause Timothy syndrome, a multisystem disorder including autism-associated phenotype." (PMID 26204268, 2015). "Pathogenic variants in CACNA1C cause Timothy syndrome (TS, MIM:601005) or Long QT syndrome, Supplementary Methods)." (PMID 41358299, 2025). "Long QT Syndrome 8 (LQT8), or Timothy Syndrome, is caused by a missense mutation in CACNA1C, which encodes the Cav1.2 component of the L-type Ca2+ channe and can lead to fatal-ventricular arrhythmias." (PMID 36742199, 2022). "However, there are descriptions that hypoglycemia may remarkably occur in 36% of patients with CACNA1C-associated Timothy syndrome, further suggesting a role of CACNA1C for human insulin secretion and blood glucose regulation." (PMID 35897673, 2022). "Timothy syndrome (TS) is a rare childhood disorder that has only been associated with the Cacna1c gene." (PMID 35326393, 2022). "Timothy syndrome (TS) is a rare autosomal-dominant disorder caused by mutation of the l-type calcium channel (CACNA1C)." (PMID 34332630, 2021). "Point mutations in CACNA1C gene, which encode for l-type voltage-gated Ca2+ channel Cav1.2, lead to Timothy syndrome (TS), a disorder affecting multiple organs and characterized by an autistic phenotype." (PMID 33167418, 2020). "Timothy syndrome (TS) is a severe ASD-related neurodevelopmental disorder caused by mutations in the CACNA1C gene, encoding the CaV1.2 calcium channel." (PMID 32393347, 2020). "Therefore, this risk variant may be associated with a gain-of-function of CACNA1C that could disrupt axon development in a way analogous to the Timothy syndrome mutation." (PMID 31805042, 2019). "Mutations found in the mutually exclusive exons 8 and 8a of the human CACNA1C gene that encodes the CaV1.2 channel are associated with the multi-organ disorder named Timothy syndrome (TS)." (PMID 29186814, 2017). "Similarly, CACNA1C mutations cause LQT8 in Timothy syndrome." (PMID 27242528, 2016). "Timothy syndrome (TS) is among the most severe forms of LQTS, caused by gain-of-function mutations in the CACNA1C gene, which encodes the L-type calcium channel CaV1.2." (PMID 40992506, 2025). "For example, mutations in CACNA1C and TCF4 are known to cause Timothy syndrome and Pitts-Hopkins syndrome respectively." (PMID 39237719, 2025).
Timothy syndrome (continued). "The first identified CACNA1C-related disorder, referred to as Timothy syndrome, consists of the combination of prolonged QT interval, autism, and cardiovascular malformation with syndactyly of the fingers and toes." (PMID 41311988, 2025). "Pathogenic variants affecting components of voltage-gated calcium channels such as CACNA1C and calmodulin and its subtypes such as CALM1, CALM2, CALM3, and caveolin-3 can cause arrhythmias, LQTS, and Timothy syndrome." (PMID 38666937, 2024). "Cacna1c is of particular interest, because a specific gain-of-function mutation (G406R) in its encoded protein is responsible for Timothy Syndrome (TS) that is clinically manifested by small teeth and dysmorphic facial features beyond classical cardiac arrhythmia." (PMID 36742392, 2023). "Interestingly, iPSC‐derived neurons from Timothy syndrome (TS) patients, which carry a gain‐of‐function mutation in the CACNA1C gene, are prone to activity‐dependent dendrite retraction." (PMID 35969184, 2022). "Gain-of-function mutations in the calcium voltage-gated channel subunit alpha 1 C (CACNA1C) gene, encoding the α1 subunit of CaV1.2, are known to cause Timothy syndrome (TS) by inducing intracellular Ca2+ overload due to a loss of voltage-dependent channel inactivation." (PMID 35897673, 2022). "Single-gene cell models are adequate for studying monogenic forms of mental disorders, such as Timothy syndrome, a monogenic form of ASD caused by loss-of-function mutations in CACNA1C (Calcium Voltage-Gated Channel Subunit Alpha1 C)." (PMID 36613684, 2022). "Of these potential binding partners, we focus on CaV1 because human CACNA1C (which encodes a CaV1 α-subunit) is mutated in Timothy Syndrome (TS), a rare monogenic form of ASD, and polymorphisms linked to CACNA1C are associated with multiple psychiatric disorders." (PMID 35266450, 2022). "For instance, CACNA1C up-regulation in schizophrenia and bipolar disorder parietal cortices and implication of CACN1C variants in Timothy syndrome, depression, schizophrenia, bipolar disorder, and impairment of working memory and verbal fluency." (PMID 34210021, 2021). "Indeed, mouse models of LQT8 (Timothy Syndrome) linked to LTCC gain-of-function mutations in CACNA1C also show increase in SR Ca2+ content and increased frequency of spontaneous Ca2+ waves in ventricular myocytes." (PMID 33404893, 2021). "These ASD genes included the Dravet syndrome gene SCN1A and the Timothy syndrome gene CACNA1C, but also GRIN2B, HTR2A, PCDH9, and other genes." (PMID 34188164, 2021). "The genetic defects of CACNA1C can precipitate many cardiac syndromes, such as Timothy syndrome (TS), long QT syndrome (LQTS), BrS, and ERS." (PMID 34222376, 2021). "In both human CACNA1C and C. elegans EGL-19, this Timothy syndrome mutation is a gain-of-function variant: it disrupts slow inactivation of the voltage-gated channel, thereby increasing calcium permeation." (PMID 31805042, 2019). "For instance, CACNA1C disruption in Timothy Syndrome produces small, misplaced teeth due to enamel hypoplasia." (PMID 30319441, 2018). "Two canonical mutations in CACNA1C (p.G406R and p.G402S) are associated with a severe LQT8, namely Timothy syndrome (TS)." (PMID 30027834, 2018). "TRPM4 enlarges the subgroup of LQT genes (KCNJ2 in Andersen syndrome and CACNA1C in Timothy syndrome) known to increase the QT interval through a more complex pleiotropic effect than merely action potential alteration." (PMID 28315637, 2017). "LQT8, also known as Timothy syndrome, is a very rare, multisystem LQTS subtype caused by a single-amino-acid substitution in exon 8a of CACNA1C, which encodes a subunit of the L-type Ca2+ channel." (PMID 28883014, 2017). "LQT syndrome type 8 (LQT8), also known as Timothy syndrome (TS), is a rare disease caused by a single amino acid substitution in exon 8a of CACNA1C, the gene encoding for CaV1.2 in humans." (PMID 26274955, 2015).
Timothy syndrome (continued). "A first hint to unravel pathophysiological pathway of ASD came from the identification of the mutation p.G406R found in the L-type calcium channel pore-forming subunit (CaV1.2) gene CACNA1C in patients with Timothy Syndrome (TS)." (PMID 24752249, 2014). "Mutations within CACNA1C have been identified in LQTS, as well as Timothy syndrome, a disease characterized by QT prolongation and extracardiac abnormalities." (PMID 25184293, 2014). "Mutations in the CACNA1C gene have been implicated in various cardiac arrhythmia syndromes, including Brugada syndrome (BrS) and long QT syndrome type 8 (LQTS8, also known as Timothy syndrome)." (PMID 40722809, 2025). "Timothy syndrome (TS) is a rare autosomal dominant disorder caused by de novo gain of function mutations in CACNA1C, the gene encoding the pore-forming α−1 subunit of the L-type voltage-gated calcium channel (LTCC) CaV1.2." (PMID 40568156, 2025). "Finally, we present minimum expected standards of clinical care for individuals with CACNA1C-Related Disorder or Timothy Syndrome, with implications for long-term management and improved outcomes for affected individuals." (PMID 41333400, 2025). "Studies have shown that the Rem2 protein can interact with CACNA1C and modulate its activity, suggesting that the Rem2 gene may be involved in the pathogenesis of Timothy syndrome." (PMID 38978817, 2024). "The cohort was extended with an adjunctive case (a patient with CACNA1C associated neurological predominant phenotype and clinical features of Timothy syndrome without conduction defects) from our genetic department." (PMID 38790536, 2024). "Why these dental and gingival anomalies are reported only in association with the typical Timothy syndrome and have never been described in the neurologically isolated CACNA1C disorders is still unexplained." (PMID 38790536, 2024). "The gene CACNA1C was reported to have a moderate evidence for disease causation in the absence of multiorgan involvement as in Timothy syndrome." (PMID 34031550, 2021). "The level of evidence for the gene KCNJ2 was only limited for the cardio-specific phenotype of LQTS, whereas both genes (CACNA1C and KCNJ2) were classified to have definitive evidence for causing multiorgan syndromes (respectively: Timothy syndrome and Andersen-Tawil syndrome)." (PMID 34031550, 2021). "For example, CACNA1C (encoding calcium channel CaV1.2) contains a locus with genome-wide evidence for association with schizophrenia, BD, and MDD and is the single-gene cause of Timothy syndrome, a disorder of multiorgan maldevelopment." (PMID 33965196, 2021). "Cav1.2 channels are located in the cardiovascular system, the nervous system, and endocrine glands, where they serve important physiopathological functions; for example, gain-of-function mutations in the CACNA1C gene cause Timothy Syndrome." (PMID 35111050, 2021). "Two genes, CACNA1C and KCNJ2, were reported to be associated with multiple organ system involvement (Timothy Syndrome and Andersen-Tawil Syndrome, respectively), which include a prolonged QT interval and ventricular arrhythmias as part of the phenotypic expression." (PMID 31983240, 2020). "Timothy syndrome (TS) is a rare genetic disorder caused by mutations in the CACNA1C gene, which encodes the L-type calcium channel α1 CaV1.2 subunit." (PMID 40576621, 2025). "Thus, we propose that Timothy syndrome and CACNA1C related disorder present as a spectrum of symptoms, with any patient harboring a CACNA1C allele at potential risk for both cardiac and non-cardiac phenotypes regardless of the initial diagnosis, making the nsLQT8 diagnosis a misnomer." (PMID 39580446, 2024). "Gain-of-function mutations within the CACNA1C gene, coding for CaVα1C, are associated with the LQTS type 8 also referred to as Timothy syndrome (TS)." (PMID 36273583, 2022).